TF (transferrin)
Diseases named in the same sentence as TF in open-access papers (continued):
Sharing a sentence is not in itself a finding about the gene and the disease.
rheumatic diseases (3 papers, 2018 to 2022). "A classification and regression tree (CART) analysis showed that the cut-off points of ≥3 mg/day prednisolone (PSL) treatment and <16.54% as the transferrin saturation (TSAT) value would best predict RLS in rheumatic disease." (PMID 32197267, 2020). "The concentrations of transferrin and other acute phase proteins have been studied in a number of rheumatic diseases in both the adults and pediatric patients." (PMID 29761223, 2018). "There are no published data on the alterations in transferrin isoforms in rheumatic diseases during growth." (PMID 29761223, 2018).
sarcoidosis (3 papers, 2016 to 2022). Sarcoidosis is a multisystemic disorder of unknown cause characterized by the formation of immune granulomas in involved organs. "Supporting the importance of transferrin and iron for lymphocytes in the lungs, transferrin levels in the BALF of patients with COPD and sarcoidosis correlate with the number of lymphocytes in the BALF." (PMID 33926483, 2021). "Several proteins were identified with higher abundance in BAL of sarcoidosis patients, including cadherin 5 (CDH5), transferrin (TF), C-C motif chemokine 24 (CCL24), interleukin 15 (IL15) apolipoprotein A (LPA) and mitochondrial superoxide dismutase (SOD2)." (PMID 27259755, 2016).
schistosomiasis (3 papers, 2013 to 2022). An infectious disease caused by parasitic trematodes of the genus Schistosoma that colonize human blood vessels and release eggs that can cause granulomatous reactions leading to acute (swimmer's itch or acute schistosomiasis syndrome) or chronic disease. "Genetic variation within cytokine and TF genes that are associated with schistosomiasis are often also associated with perturbation to the TH1/TH2 balance and the expression of cytokines involved in responding to infection." (PMID 35759449, 2022). "Here we present the frequencies of single nucleotide polymorphisms (SNPs) in cytokine and TF genes in a Zimbabwean population, and further relate SNPs to susceptibility to schistosomiasis and cytokine levels." (PMID 35759449, 2022). "In human and murine schistosomiasis, serum transferrin levels have varied substantially between studies." (PMID 27138990, 2016). "In addition, increased TF expression is present in monocytes from hepatosplenic schistosomiasis patients, compared to monocytes of healthy donors, suggesting the involvement of monocyte TF expression in the prothrombotic state observed in schistosomiasis patients." (PMID 24385897, 2013). "Furthermore, elevated levels of tumor necrosis factor alpha (TNF-α) are present in schistosomiasis patients, and high TNF-α levels are known to induce TF expression on endothelial cells in vitro." (PMID 24385897, 2013).
thymoma (3 papers, 2015 to 2022). A neoplasm arising from the epithelial cells of the thymus. "LIPE, MYH6, ACTG2, KLF4, SULT4A1, and TF were the key genes affecting the prognosis of thymoma." (PMID 34104648, 2021). "This study identified key genes related to the prognosis of thymoma, including LIPE, MYH6, ACTG2, KLF4, SULT4A1, and TF." (PMID 34104648, 2021). "By screening the DEGs that had a significant impact on the prognosis of thymoma, we identified LIPE, MYH6, ACTG2, KLF4, SULT4A1, and TF as key genes." (PMID 34104648, 2021). "ACTG2, KLF4, SULT4A1, and TF were all involved in the occurrence or development of cancer, but their biological significance in thymoma was not clear." (PMID 34104648, 2021). "The “TF-lncRNA” core network map for MG patients without thymoma versus MG patients with thymoma indicated that TF TAF1 modulated the expression of 8 lncRNAs." (PMID 25889429, 2015).
vitamin deficiencies (3 papers, 2017 to 2026). "In a subgroup of anemic patients in remission, hence without ACD interference, transferrin tended to be elevated (data not shown), consistently with observations on persisting iron and vitamin deficiencies in inactive IBD." (PMID 29226154, 2017).
acute liver failure (2 papers, 2018 to 2021). Rapid deterioration of liver function causing encephalopathy and coagulopathy. "In critically ill patients and individuals with decompensated liver cirrhosis, severe alcoholic hepatitis (AH), or acute liver failure, low transferrin levels associate with increased mortality." (PMID 33593348, 2021). "Prospective studies are warranted to corroborate the relationship between HNF4α and transferrin levels in several forms of liver failure, i.e., acute liver failure, acute-on-chronic liver failure, and AH." (PMID 33593348, 2021).
acute pancreatitis (2 papers, 2022 to 2025). An acute inflammatory process that leads to necrosis of the pancreatic parenchyma. "In this study, we did not observe any changes in all the studied laboratory tests, including transferrin isoforms, between the edematous and necrotizing forms of acute pancreatitis." (PMID 35329964, 2022). "Among the other isoforms of transferrin, only the concentration of 4-sialoTf was significantly higher in the acute pancreatitis group than that in the controls (p = 0.011)." (PMID 35329964, 2022). "As expected, we obtained a decreased total concentration of transferrin, with lower level in acute pancreatitis than that in the chronic one." (PMID 35329964, 2022). "It has been also shown that transferrin sialylation can be a potential prognostic marker for the severity of acute pancreatitis." (PMID 35329964, 2022). "The concentration of 4-sialoTf, among other isoforms of transferrin, was exclusively one to be significantly higher in acute pancreatitis group than that in the controls." (PMID 35329964, 2022).
alcoholic hepatitis (2 papers, 2021 to 2023). Acute hepatitis resulting from ingestion of alcohol. "Factors regulating transferrin expression in alcoholic hepatitis (AH) were assessed via transcriptomic/methylomic analysis as well as chromatin immunoprecipitation coupled to DNA sequencing." (PMID 33593348, 2021).
astrocytomas (2 papers, 2000 to 2014). "First, TF expression in endothelial cells which was observed in 74% of glioblastomas, 54% of anaplastic astrocytomas and none of low-grade astrocytomas, correlated with the microvascular density of the tumours." (PMID 10864205, 2000).
autism (2 papers, 2015 to 2022). Persistent deficits in social interaction and communication and interaction as well as a markedly restricted repertoire of activity and interest as well as repetitive patterns of behavior. "Using the IVW method, no significantly causal link between serum iron and ferritin levels and transferrin saturation on autism was observed in both PGC and FinnGen Consortium datasets." (PMID 36407516, 2022). "A further meta-analysis based on the two independent data showed that serum transferrin remained associated with an increased risk of autism (OR = 1.16, 95% CI: 1.03–1.30, p = 0.013)." (PMID 36407516, 2022). "In summary, the results of this MR study demonstrate that genetically predicted serum transferrin levels might be causally associated with an increased risk of autism." (PMID 36407516, 2022). "Using the IVW method, our results demonstrated that genetically predicted serum transferrin was causally associated with an increased risk of autism, indicating that transferrin may be a potential marker for autism development." (PMID 36407516, 2022). "Using the inverse-variance weighted (IVW) method, the combined results of PGC and FC demonstrated that genetically determined serum transferrin level was significantly associated with an increased risk of autism [odds ratio (OR) = 1.16, 95% CI: 1.03–1.30, p = 0.013]." (PMID 36407516, 2022). "Thus, we performed two-sample Mendelian randomization (MR) analysis to evaluate the causal link between iron status on autism, using genetic instruments (p < 5E–08) strongly associated with iron status (N = 48,972), including serum iron, ferritin, transferrin levels, and transferrin saturation." (PMID 36407516, 2022). "Thus, a current challenge for researchers is to determine the underlying mechanisms contributing to the association between an elevation of transferrin and autism risk, which is important for establishing prevention strategies in patients with autism susceptibility." (PMID 36407516, 2022). "In addition, transferrin also was reported to have an anti-oxidative function, which could further reduce the risk of autism." (PMID 36407516, 2022). "No obvious horizontal pleiotropy and heterogeneity were found in the MR analysis between serum iron, transferrin, and transferrin saturation and autism." (PMID 36407516, 2022). "There was no significant causal effect of serum iron (OR = 0.99, 95% CI: 0.72–1.37, p = 0.951), ferritin (OR = 0.88, 95% CI: 0.47–1.64, p = 0.676), and transferrin saturation (OR = 0.89, 95% CI: 0.72–1.09, p = 0.252) on autism." (PMID 36407516, 2022). "In this study, we found that only serum transferrin was associated with an increased risk of autism, but not serum iron, ferritin, and transferrin saturation." (PMID 36407516, 2022). "Using the IVW method, genetically predicted serum transferrin was significantly associated with an increased risk of autism in PGC (OR = 1.16, 95% CI: 1.03–1.31, p = 0.018), but not FinnGen Consortium (OR = 1.15, 95% CI: 0.80–1.65, p = 0.451)." (PMID 36407516, 2022). "Second, although the combined estimates of the meta-analysis showed serum transferrin was associated with an increased risk of autism, the causal effect obtained from FinnGen Consortium was not statistically significant." (PMID 36407516, 2022). "Meanwhile, the results of the meta-analysis showed that genetically determined serum transferrin was still significantly associated with an increased risk of autism, even if using the negative result from FinnGen Consortium, indicating our results were robust." (PMID 36407516, 2022). "Due to the elevation of transferrin often happening earlier than the reduction of serum iron, it might contribute to a positive association between autism and serum transferrin, but not iron." (PMID 36407516, 2022). "Similarly, our results showed that only transferrin was significantly associated with autism risk, but not serum iron levels." (PMID 36407516, 2022).
autism (continued). "Contrarily, the serum levels of major antioxidant proteins, transferrin (iron-binding protein) and ceruloplasmin (copper-binding protein), were found to be significantly decreased in children with autism compared to their non-autistic siblings." (PMID 25769033, 2015). "Finally, although the MR results of serum transferrin using the latest autism GWAS dataset of iPSYCH-PGC were not statistically significant, the causal estimates showed a similar trend and were significant in the meta-analysis." (PMID 36407516, 2022).
autoimmune hepatitis (2 papers, 2015 to 2023). Hepatitis caused by autoantibodies. "We used TF-OVA mice, which express ovalbumin in hepatocytes, to investigate the impact of Treg in a model of autoimmune hepatitis." (PMID 26599014, 2015).
Autoimmunity (2 papers, 2016 to 2022). The occurrence of an immune reaction against the organism's own cells or tissues. "However, hierarchical cluster analysis of the TF suggested transcriptional organization by organ of origin or presence of autoimmunity." (PMID 35271505, 2022).
bone fracture (2 papers, 2018 to 2026). "Transferrin saturation was associated with mobility and all measured functional outcomes two months after hip fractures." (PMID 41543817, 2026). "Thus, we conclude that serum transferrin is a good marker to preoperatively judge the likelihood of patient developing postoperative wound infection in closed long bone fracture cases." (PMID 30123800, 2018).
brain glioma (2 papers, 2014 to 2021). A malignant glioma that involves the brain. "Liposome (LP) was used to conjugate the cyclic RGD and TFs to establish the brain glioma cascade delivery system (RGD/TF-LP)." (PMID 25289086, 2014). "Doxorubicin-loaded liposomes targeted with folate and transferrin were proven effective in penetrating the BBB and targeting the brain glioma." (PMID 33802531, 2021). "TF targeting LPs have been reported to increase the BBB penetration of the encapsulated drug and thereby improve the therapeutic efficacy towards brain glioma in vivo." (PMID 25289086, 2014).
brain trauma (2 papers, 2014 to 2024). "The extent and intensity of head impacts and serum values of S100B, UCH-L1, and beta-2 transferrin were measured pre- and post-game from 15 college football players who did not experience a concussion after a game." (PMID 24806476, 2014).
Cachexia (2 papers, 2024). Severe weight loss, wasting of muscle, loss of appetite, and general debility related to a chronic disease. "In multivariate Cox analysis, we found that the risks of reduced long-term survival in cancer cachexia patients with low albumin, prealbumin and transferrin levels were 1.51, 1.42, and 1.50 times higher than those with high hepatic protein levels." (PMID 38438901, 2024). "The risks of 90-days mortality and impaired QoL were higher in cachexia patients with low albumin, prealbumin, and transferrin levels." (PMID 38438901, 2024). "Thus, the present study specifically set optimal cutoff values of albumin, prealbumin and transferrin for cancer cachexia population determined by standardized log-rank statistics, with figures of 38.7, 0.17, and 2.29 g/L respectively." (PMID 38438901, 2024). "Cancer cachexia patients were more likely to be male, older, have a history of smoking and drinking, have advanced tumor stage, ECOG grade > 1, lower BMI, calf circumference and hand grip strength, increased NLR, and decreased albumin, prealbumin, and transferrin levels." (PMID 38438901, 2024).
cerebral infarction (2 papers, 2021 to 2023). An ischemic condition of the brain, producing a persistent focal neurological deficit in the area of distribution of the cerebral arteries. "Trousseau syndrome is a known condition in which cancer patients exhibit cerebral infarction, and one of the mechanisms is thought to involve increased TF expression by tumor cells." (PMID 37676492, 2023).
chlamydia (2 papers, 2014 to 2021). "A total of 4 studies reported only ocular chlamydia prevalence, 4 reported only active TF levels, and 13 reported both ocular chlamydia and active TF." (PMID 34237074, 2021). "Note that some chlamydial infection still exists when TF prevalence is below 10%, indicating the potential ongoing need for MDA." (PMID 24722392, 2014).
chronic obstructive pulmonary disease (2 papers, 2022 to 2023). A chronic and progressive lung disorder characterized by the loss of elasticity of the bronchial tree and the air sacs, destruction of the air sacs wall, thickening of the bronchial wall, and mucous accumulation in the bronchial tree. "COX univariate analysis showed that mortality within 6 months was associated with leucine > 174 μM or <109 μM, age, APACHE II and SOFA scores, chronic obstructive pulmonary disease, and levels of C-reactive protein, cholesterol, albumin, prealbumin, and transferrin." (PMID 35035612, 2022). "Either after adjusting for age and chronic obstructive pulmonary disease or after adjusting for age, chronic obstructive pulmonary disease, C-reactive protein, cholesterol, albumin, pre-albumin, and transferrin, leucine > 174 μM remained an independent predictor of mortality within 6 months." (PMID 35035612, 2022).
coronary atherosclerosis (2 papers, 2020 to 2025). Atherosclerosis of the coronary vasculature. "Furthermore, higher iron status exerted a detrimental effect on VVs of lower extremities in both genders (P < 0.05) and a protective effect on male patients with coronary atherosclerosis (P < 0.05 for serum iron, ferritin, and transferrin saturation, respectively)." (PMID 33195696, 2020). "The results demonstrated that iron status had a significant causal effect on VVs of lower extremities (P < 0.001) and a potential effect on coronary atherosclerosis (P < 0.05 for serum iron, ferritin, and transferrin saturation, respectively), but not on other VDs." (PMID 33195696, 2020).
Down syndrome (2 papers, 2019 to 2022). "It has been reported that the iron saturation of transferrin is higher in AD and Down syndrome groups when compared with the controls, but the mechanism of transferrin in AD is unclear." (PMID 31816602, 2019).
dyslipidaemia (2 papers, 2019 to 2024). "Most importantly, higher concentrations of transferrin and sTfR were related to lower dyslipidaemia risk (OR for transferrin: 0.49, 95% CI: 0.33–0.71; OR for sTfR: 0.68, 95% CI: 0.46–0.99)." (PMID 30755213, 2019). "Most importantly, the levels of transferrin and sTfR were inversely related to the risk of dyslipidaemia in children and adolescents with different BMI." (PMID 30755213, 2019). "This table indicates that the risk of dyslipidaemia significantly decreased over the quartiles of transferrin and sTfR concentrations, suggesting that the risk of dyslipidaemia was inversely correlated with both transferrin and sTfR concentrations." (PMID 30755213, 2019). "Moreover, an inverse relationship was observed between transferrin and sTfR concentrations and dyslipidaemia risk in children with different BMI." (PMID 30755213, 2019). "However, studies on the relationship between transferrin, sTfR and the risk of dyslipidaemia are still limited, especially in children." (PMID 30755213, 2019). "The present study also revealed that transferrin and sTfR concentrations were inversely associated with the risk of dyslipidaemia in human beings; however, the underlying mechanisms of the relationship are largely unknown." (PMID 30755213, 2019). "Subjects with dyslipidaemia had lower SF, transferrin and sTfR levels by different BMI categories, and those who were obese had higher ferritin levels (all P < 0.05)." (PMID 30755213, 2019). "Still, there is scarce evidence on the relationship between transferrin and sTfR levels and dyslipidaemia, especially in children." (PMID 30755213, 2019). "On the other hand, children and adolescents with dyslipidaemia had lower levels of serum iron, transferrin and sTfR, and higher ferritin levels in those who were obese." (PMID 30755213, 2019). "Alternatively, it is possible that dyslipidaemia contributes to iron metabolism disorders, resulting in decreased transferrin and sTfR." (PMID 30755213, 2019). "As decreased transferrin and sTfR concentrations indicate reduced bone marrow erythropoietic activity, it could be inferred that erythropoiesis is less active in children and adolescents with dyslipidaemia." (PMID 30755213, 2019). "In the present study, we observed that levels of transferrin and sTfR in children with dyslipidaemia were lower than subjects without dyslipidaemia, although the concentrations of transferrin and sTfR in this study did not significantly differ by BMI categories." (PMID 30755213, 2019). "However, children and adolescents with dyslipidaemia had lower levels of both transferrin and sTfR concentrations compared to those without dyslipidaemia." (PMID 30755213, 2019).
enteritis (2 papers, 2019 to 2023). Inflammation of the small intestine. "In terms of irinotecan-induced chemotherapeutic enteritis, ozone inhibits TF expression by activating the AMPK/SOCS3 pathway, thereby alleviating chemotherapeutic enteritis caused by ischemic–hypoxic injury." (PMID 37765024, 2023).
food allergies (2 papers, 2022 to 2023). "In a large retrospective study including children with food allergy and other atopic conditions, vitamin D deficiency was detected in one-third of all children, and an association of food allergy to lower iron and transferrin saturation levels and a higher eosinophil percentage were described." (PMID 36698466, 2022).